SDC1 (syndecan 1)
Diseases named in the same sentence as SDC1 in open-access papers (continued):
Sharing a sentence is not in itself a finding about the gene and the disease.
liver cancer (8 papers, 2012 to 2025). An epithelial or non-epithelial malignant neoplasm that arises from the liver. "Moreover, syndecan-1 increased significantly with increasing stage of Barcelona-Clinic Liver Cancer Group diagnostic and treatment strategy." (PMID 22396913, 2012). "Several studies have indicated that SDC1 plays an important role in the development of colon, pancreatic, breast and liver cancers, few studies on SDC1 in pan-cancer have been published." (PMID 41364407, 2025). "In contrast, in human liver cancer, syndecan-1 expression decreases, or even disappears, whereas the cytoplasm is filled with SPOCK1." (PMID 35186754, 2022). "These complex mechanisms mimic the characteristics of nonalcoholic steatohepatitis (NASH) induced human liver cancer successfully delayed by syndecan-1." (PMID 33801718, 2021). "The significance of quantitative changes of syndecan-1 in liver cancer is still not clearly understood." (PMID 32977498, 2020). "Despite the abundance of relevant histological data, very little is known about the actual role of syndecan-1 in liver cancer." (PMID 32977498, 2020). "Furthermore, proteoglycans such as endocan and syndecan-1 in the serum of patients with alcoholic cirrhosis are potential prognostic biomarkers for liver cancer." (PMID 36297027, 2022). "In this work, we aimed to dissect the roles of SDC1 in the development of liver cancer." (PMID 33801718, 2021).
malaria (8 papers, 2015 to 2024). Malaria is a serious and sometimes fatal disease caused by a parasite that commonly infects a certain type of mosquito which feeds on humans. "CS and CSPGs play crucial roles in malaria pathogenesis, and syndecan-1 (SDC1) is the major CSPG involved in pregnancy-associated Plasmodium falciparum malaria." (PMID 34503301, 2021). "In this study we found that ADMA was increased in severe knowlesi malaria, and was associated with both syndecan-1 and urinary GAGs." (PMID 33963210, 2021). "In knowlesi malaria, in logistic regression models syndecan-1 was also independently associated with both severe disease and AKI." (PMID 33963210, 2021). "Syndecan-1 concentrations were found to be elevated in severe malaria cases due to eCGx damage, and this was negatively correlated with RBC and PLT9." (PMID 38839816, 2024). "We also found independent inverse correlations between platelets and both syndecan-1 and GAGs, in both vivax and knowlesi malaria." (PMID 33963210, 2021). "In patients with knowlesi malaria, biomarkers of severity were more closely correlated with syndecan-1 than with urinary GAGs." (PMID 33963210, 2021). "In knowlesi malaria, syndecan-1 was also inversely correlated with platelet count on enrolment (r = − 0.23, p = 0.001), again remaining significant after controlling for parasitemia (r = − 0.23, p = 0.001)." (PMID 33963210, 2021). "A notable finding is our study was the inverse correlation in knowlesi malaria between syndecan-1 and haemoglobin, with this correlation remaining significant after controlling for parasitemia and fever duration." (PMID 33963210, 2021). "In knowlesi malaria, plasma syndecan-1 was also highest in those with severe disease, and correlated with markers of endothelial activation (angiopoietin-2, osteoprotegerin, ICAM-1), asymmetric dimethylarginine (ADMA) and impaired microvascular reactivity." (PMID 33963210, 2021). "In patients with knowlesi malaria, median plasma syndecan-1 was higher in males compared to females (187 [IQR 123–307] vs. 133 [IQR 95–264] ng/ml, p = 0.014)." (PMID 33963210, 2021). "In patients with knowlesi malaria, syndecan-1 was higher and S-1-P lower, in males compared to females." (PMID 33963210, 2021). "In patients with knowlesi malaria, syndecan-1 was inversely correlated with haemoglobin on enrolment (r = − 0.23, p = 0.001), remaining significant after controlling for parasitemia and fever duration (p < 0.0001)." (PMID 33963210, 2021). "This validates the data collected with rVAR2 showing that SDC1 is the placental receptor for the placental malaria parasites and shows that the binding specificity is retained within the recombinant VAR2CSA proteins." (PMID 27556547, 2016). "In 32 loci passing quality control procedures, we found polymorphisms in USP38, FREM3, SDC1, DDC, and LOC727982 genes to be putatively associated with differential susceptibility to severe malaria." (PMID 25805752, 2015). "The rs11899121 (SDC1) and rs10188961 (LOC727982) polymorphisms were associated with respiratory distress and acidosis, respectively, as well as with severe malaria per se." (PMID 25805752, 2015). "In Malaysian patients with knowlesi (n = 200) and vivax (n = 61) malaria, and in healthy controls (n = 50), we measured glycocalyx breakdown products plasma syndecan-1 and urinary glycosaminoglycans, and evaluated correlations with biomarkers of disease severity." (PMID 33963210, 2021). "In the patients with knowlesi malaria, the eGC breakdown marker syndecan-1 was also significantly related to acute kidney injury, supporting the notion that glomerular glycocalyx degradation is a key mechanism of acute kidney injury in malaria and other acute infections." (PMID 34858979, 2021).
malaria (continued). "Plasma concentrations of syndecan-1 were correlated with duration of fever in knowlesi malaria (r = 0.30, p < 0.0001) and in vivax malaria (r = 0.49, p < 0.001); in both species this remained significant after controlling for parasitemia (knowlesi malaria: p < 0.001; vivax malaria: p = 0.020)." (PMID 33963210, 2021). "Interestingly we found that in severe knowlesi malaria, syndecan-1 was as high in females compared to males, suggesting that severe disease in females may be associated with a greater proportionate loss of glycocalyx." (PMID 33963210, 2021). "In knowlesi malaria, the difference in median syndecan-1 between severe and non-severe disease was more marked in females than males." (PMID 33963210, 2021). "Plasma concentrations of syndecan-1 were correlated with urinary GAGs in knowlesi malaria (r = 0.21, p = 0.019), although this did not remain significant after controlling for parasitemia." (PMID 33963210, 2021). "There was a weak correlation between age and syndecan-1 in patients with knowlesi malaria (r = 0.16, p = 0.027); however, this did not remain significant after controlling for parasitemia." (PMID 33963210, 2021). "Thus, in females, median syndecan-1 was 2.6-fold higher in severe compared to non-severe knowlesi malaria, while in males, the median was only 1.7-fold higher." (PMID 33963210, 2021).
Obesity (8 papers, 2012 to 2025). Accumulation of substantial excess body fat. "There are some studies indicating that syndecan-1 concentrations are elevated both in obesity and T2D." (PMID 39943818, 2025). "Transgenic overexpression of SDC1 in the hypothalamus promotes obesity due to increased food intake as overabundant SDC1 at the cell membrane interacts with AgRP to potentiate its orexigenic activity." (PMID 32508807, 2020). "The first observation associating a HSPG with appetite regulation was maturity-onset obesity in transgenic mice over-expressing syndecan-1." (PMID 22479599, 2012). "Further elucidating the mechanism by which SDC1, and possibly other syndecans, regulates differentiation of MSCs could lead to new therapeutic targets in metabolic disorders such as obesity." (PMID 38912739, 2024). "In this study, we report marked alterations in concentrations of 2 circulating biomarkers of the vascular endothelial glycocalyx, HA, and syndecan-1, 2 years after bariatric surgery in patients with obesity, with as well as without T2D." (PMID 39943818, 2025).
periodontitis (8 papers, 2019 to 2026). An acute or chronic inflammatory process that affects the tissues that surround and support the teeth. "Furthermore, soluble syndecan-3 occurred naturally in the sera of patients with rheumatoid arthritis and periodontitis, and its levels correlated with syndecan-1." (PMID 31300004, 2019). "While the true function of shedding may not yet fully be understood, increases in serum concentrations of syndecan-1 have been detected in chronic kidney disease, inflammatory bowel disease, systemic lupus erythematosus and periodontitis." (PMID 31300004, 2019). "Of all investigated factors, the expression domains of Sdc1, HPSE1, EXT1, and NDST1 in gingival tissue displayed statistically significant differences between control and periodontitis group." (PMID 31611818, 2019). "However, the stromal expression domains of Sdc1 (p = 1,1033 × 10–6), HPSE1 (p = 0,0023), EXT1 (p = 1,2849 × 10–7), NDST1 (p = 0,000105), and CD45 (p = 0,003747) showed significant difference between controls and periodontitis group." (PMID 31611818, 2019).
Pleural effusion (8 papers, 2012 to 2025). The presence of an excessive amount of fluid in the pleural cavity. "In this study we analyse the role of soluble syndecan-1 for its diagnostic and prognostic importance in pleural effusions and serum from patients with malignant diseases." (PMID 25147801, 2014). "This study aimed to evaluate the diagnostic and prognostic performance of soluble syndecan-1 in patients' serum and pleural effusions." (PMID 25147801, 2014). "Using two cohorts of patients, we assessed the diagnostic and prognostic value of soluble syndecan-1 in pleural effusions and sera, using enzyme-linked immunosorbent assays." (PMID 25147801, 2014). "Pleural effusion Galectin-1, NRG1-β1, Osteopontin, Mesothelin, shed SDC-1, VEGF and TIMP-1 levels are more reliable diagnostic biomarkers than HGF and MMP in pleural effusion." (PMID 32731396, 2020). "In order to evaluate the correlation between ELISA and Luminex immunoassays, pleural effusion levels of shed SDC-1, Mesothelin and VEGF were measured independently by both immunoassays." (PMID 32731396, 2020). "Paired pleural effusion and serum samples showed moderate correlation of soluble syndecan-1 (r = 0.45, P = 0.05)." (PMID 25147801, 2014). "We further show that soluble syndecan-1 in pleural effusions carry strong prognostic value for patients with pleural malignancies." (PMID 25147801, 2014). "Syndecan-1 levels in pleural effusions significantly predicted malignant disease (odds ratio 8.59, 95% CI 3.67 to 20.09)." (PMID 25147801, 2014). "To assess the relationship between cell-bound and soluble syndecan-1, we performed immunocytochemistry on cells in pleural effusion samples paired with their ELISA readout of soluble syndecan-1 levels (n = 18)." (PMID 25147801, 2014). "Syndecan-1 separates malignant and benign conditions when measured in pleural effusion supernatants." (PMID 25147801, 2014). "In summary, this study describes the clinical value of analysing soluble syndecan-1 in serum and pleural effusions." (PMID 25147801, 2014). "The aim of this study is to evaluate shed SDC-1 in pleural effusions together with angiogenesis related proteins and identify optimal biomarker batteries that allow earlier diagnosis and improve the possibilities to distinguish MPM from metastatic adenocarcinoma and reactive conditions." (PMID 32731396, 2020). "Moreover, there is a negative correlation between Mesothelin and shed SDC-1 and positive correlation between VEGF, Angiopoietin-1 and shed SDC-1 level in the pleural effusion from malignant cases." (PMID 32731396, 2020). "Linear regression of staining intensity times percentage syndecan-1 reactive tumour cells (semiquantitative ICC score) and pleural effusion levels indicate a positive correlation (r = 0.36, P = 0.14)." (PMID 25147801, 2014). "In addition to this, we showed that SDC-1 and HGF had higher concentrations in exosomes derived from pleural effusion from metastatic adenocarcinoma patients." (PMID 34827604, 2021). "In order to determine the prognostic value of pleural effusion derived Angiopoietin-1, HGF, MMP-7, Osteopontin, TIMP-1, Galectin, Mesothelin, NRG1-b1, SDC-1 and VEGF, we divided patients in two groups depending on the established cut-off value for all analytes." (PMID 32731396, 2020). "In another study, SDC1 was detected in pleural effusions, but not in sera of patients with pleural metastatic disease and malignant mesothelioma." (PMID 26293675, 2015).
acute coronary syndrome (7 papers, 2021 to 2025). Signs and symptoms related to acute ischemia of the myocardium secondary to coronary artery disease. "Notably, the level of plasma soluble SDC1 in patients with acute coronary syndrome has been associated with short-term mortality and atherosclerotic plaque vulnerability." (PMID 35722091, 2022). "One study previously reported the possible role of syndecan-1 in atherogenesis; other authors even outlined the significant increase of serum syndecan-1 in patients with acute coronary syndromes." (PMID 37109427, 2023). "While this study is not powered to assess survival outcomes, a high serum hyaluronan concentration has been associated with poor survival in patients with kidney disease and syndecan-1 has been shown to be elevated in patients with acute coronary syndrome and decompensated heart failure." (PMID 33423673, 2021).
autoimmune disease (7 papers, 2017 to 2025). A disorder resulting from loss of function or tissue destruction of an organ or multiple organs, arising from humoral or cellular immune responses of the individual to their own tissue constituents. "SDC-1, a member of the transmembrane proteoglycans, plays a significant role in autoimmune diseases, with its complex involvement in both inflammation and tissue repair." (PMID 39509329, 2025). "Intriguingly, dysregulation of SDC-1 has also been suggested to play a direct role or act as a trigger in autoimmune diseases." (PMID 39509329, 2025). "Therefore, more detailed research is necessary to determine whether syndecan-1 plays a role in vascular involvement in autoimmune diseases, including Behçet’s disease, and if so, to clarify the exact mechanism of this role." (PMID 41578772, 2025). "Therefore, the DR6/syndecan-1 axis should be a novel therapeutic target in autoimmune disease." (PMID 28045014, 2017).
Autoimmunity (7 papers, 2012 to 2025). The occurrence of an immune reaction against the organism's own cells or tissues. "Emerging research has begun to highlight other biomarkers with significant implications for autoimmunity, including syndecan-1 (SDC-1)." (PMID 39509329, 2025).
Crohn disease (7 papers, 2013 to 2025). A gastrointestinal disorder characterized by chronic inflammation involving all layers of the intestinal wall, noncaseating granulomas affecting the intestinal wall and regional lymph nodes, and transmural fibrosis. "In this study, we aimed to determine the serum levels of SDC-1 and to evaluate the relationship between serum levels of SDC-1 and disease activity in Crohn's disease." (PMID 26294905, 2015). "The expression of syndecan-1 and the proinflammatory cytokine TNFα has been found to be inversely correlated in the colonic mucosa of patients with Crohn's disease." (PMID 23874391, 2013).
ductal breast carcinoma in situ (7 papers, 2007 to 2023). A carcinoma entirely confined to the mammary ducts. "Of note, co-expression of Sdc-1 and c-Met represents a signature associated with angiogenic and lymphangiogenic-related factors in ductal breast carcinoma in situ." (PMID 34066023, 2021). "Of particular relevance to the process of angiogenesis, co-expression of Sdc-1, E-cadherin, and c-Met represents a signature associated with (lymph) angiogenesis-related factors in ductal breast carcinoma in situ." (PMID 34066023, 2021). "For example, Sdc-1 expression is associated with angiogenic factors in ductal breast carcinoma in situ, its interaction with αvβ3 and αvβ5 integrins regulated angiogenesis in a murine breast cancer model, and Sdc-1 expression by stromal fibroblasts enhances tumor growth and angiogenesis." (PMID 36980251, 2023). "SDC1 expression profile in GDS3853 showed increased expression levels in ductal carcinoma in situ (DCIS) and invasive ductal carcinoma (IDC) compared with those in healthy breast tissue." (PMID 29963269, 2018). "Tiemann and colleagues studied the role of SDC1 in ductal carcinoma in situ of the breast (DCIS)." (PMID 26293675, 2015).
inflammatory bowel disease (7 papers, 2013 to 2024). A spectrum of small and large bowel inflammatory diseases of unknown etiology. "Studies in animal models have revealed a mechanistic role of SDC1 in the regulation of contact allergies, kidney inflammation, multiple sclerosis, inflammatory bowel disease, and inflammation-associated tumorigenesis." (PMID 36264388, 2022). "Second, seven of the ten patients had inflammatory bowel disease, which may have slightly increased the baseline syndecan-1 levels." (PMID 31415628, 2019). "It is believed that releasing the extracellular domain of syndecan-1 from the intestinal epithelial cells may reduce the intensity of inflammatory bowel diseases and the transmigration of neutrophils by inactivating key inflammatory mediators and reducing the expression of proinflammatory cytokines." (PMID 33923501, 2021). "Determination of the role of SDC-1, an important protein in the regulation of inflammation, control of wound healing, and protection of epithelial integrity, in the pathogenesis, diagnosis, and the follow-up of inflammatory bowel diseases (IBD) would be useful." (PMID 26294905, 2015). "Since epithelial barrier function is essential for the pathogenesis of inflammatory bowel disease, lacking the protective factor syndecan-1 in the intestine can promote inflammatory reactions." (PMID 23874391, 2013). "Moreover, the involvement of SDC-1 in fundamental processes associated with inflammatory bowel disease (IBD) such as regulation of fibrosis, control of inflammation, and wound healing and the pathogenesis and disease progression of IBD has not been fully identified." (PMID 26294905, 2015).
influenza (7 papers, 2013 to 2023). An acute viral infection of the respiratory tract, occurring in isolated cases, in epidemics, or in pandemics; it is caused by serologically different strains of viruses (influenzaviruses) designated A, B, and C, has a 3-day incubation period, and usually lasts for 3 to 10 days. "SDC-1 has an important function as a transmembrane receptor in the control of inflammation during influenza infection." (PMID 34835130, 2021).